AGPAT1 (1-acylglycerol-3-phosphate O-acyltransferase 1)
Description:
Converts 1-acyl-sn-glycerol-3-phosphate (lysophosphatidic acid or LPA) into 1,2-diacyl-sn-glycerol-3-phosphate (phosphatidic acid or PA) by incorporating an acyl moiety at the sn-2 position of the glycerol backbone.
Synonyms: LPAAT-alpha; G15; LPLAT1; 1-AGPAT1; LPAATA
Tractability: Antibody: UniProt predicts a signal peptide or a membrane-spanning region. PROTAC: ubiquitination databases record sites on it; its protein half-life has been measured.
Target class: Enzyme; Transferase
Gene: Protein-coding gene on chromosome 6 (32,168,205 to 32,178,096, reverse strand). Ensembl gene ENSG00000204310.
Subcellular location: Endoplasmic reticulum membrane
Subcellular location (Human Protein Atlas): Endoplasmic reticulum; Rods & Rings
Pathways (Reactome):
Metabolism: ChREBP activates metabolic gene expression; Synthesis of PA
Gene Ontology:
Molecular function: 1-acylglycerol-3-phosphate O-acyltransferase activity; protein binding; acyltransferase activity
Biological process: phosphatidic acid biosynthetic process; positive regulation of cytokine production; phospholipid metabolic process; positive regulation of cytokine-mediated signaling pathway; CDP-diacylglycerol biosynthetic process; phospholipid biosynthetic process
Cellular component: endoplasmic reticulum; endoplasmic reticulum membrane; membrane
Genetic constraint (gnomAD): Loss-of-function variants: 6 observed, 32.28 expected, observed/expected ratio (o/e) 0.19, 90% interval 0.1 to 0.37. The upper end of that interval is the gene's LOEUF score, 0.37, which puts it in group 1 of 6, group 1 being the genes least tolerant of losing a copy. Missense variants: 187 observed, 392.08 expected, observed/expected ratio (o/e) 0.48, 90% interval 0.42 to 0.54. Synonymous variants: 139 observed, 162.36 expected, observed/expected ratio (o/e) 0.86, 90% interval 0.75 to 0.99.
Homologues: Orthologues: chimpanzee AGPAT1 (100% identical), macaque AGPAT1 (99% identical), pig AGPAT1 (98% identical), rabbit AGPAT1 (97% identical), dog AGPAT1 (96% identical), rat Agpat1 (93% identical), guinea pig AGPAT1 (92% identical), mouse Agpat1 (91% identical), tropical clawed frog agpat1 (67% identical), Drosophila melanogaster Agpat1 (39% identical), Caenorhabditis elegans acl-2 (33% identical), Caenorhabditis elegans acl-1 (29% identical), and 1 more. Paralogues in human: AGPAT2 (46% identical).
Diseases named in the same sentence as AGPAT1 in open-access papers:
AGPAT1 is named in the same sentence as 47 diseases in open-access papers, as found by Europe PMC text mining. Sharing a sentence is not in itself a finding about the gene and the disease. The quoted sentences say what the papers report.
colorectal cancer (4 papers, 2018 to 2022). A primary or metastatic malignant neoplasm that affects the colon or rectum. "One study revealed that upregulation of genes (ABCA1, ACSL1, AGPAT1, and SCD) related to lipogenesis and cholesterol synthesis pathways was associated with poor survival outcomes in colorectal cancer patients." (PMID 34557266, 2021). "In colorectal carcinoma (CRC), expression analysis of lipid metabolism genes of patient tumor samples, as well as transcriptomic meta-analysis studies of CRC patient data, showed that the increased expression of AGPAT1 is associated with a high risk of relapse and shorter survival." (PMID 35008394, 2022). "The genomic coding sequence of ABCA1, ACSL1, AGPAT1 and SCD genes, as well as, their differential expression in a genome-wide expression meta-analysis in colorectal cancer patients were explored." (PMID 29464044, 2018).
colon cancer (3 papers, 2015 to 2023). "Overexpression of SCD-1 and other enzymes, namely ATP-binding cassette sub-family A member (ABCA1), long chain acyl-CoA synthetase (ACSL1) and 1-acyl-sn-glycerol-3-phosphate acyltransferase alpha (AGPAT1), was associated with increased risk of recurrence and worse outcomes in stage II colon cancer." (PMID 30684960, 2019). "The combined analysis of these 4 genes, ABCA1, ACSL1, AGPAT1 and SCD, constitutes a metabolic-signature (ColoLipidGene) able to accurately stratify stage II colon cancer patients with 5-fold higher risk of relapse with strong statistical power in the four independent groups of patients." (PMID 25749516, 2015). "The model including the four LMGs (ABCA1, ACSL1, AGPAT1 and SCD) is proposed as a prognostic marker of colon cancer with stage II, but not effective in all stages of colon cancer." (PMID 37055842, 2023).
Parkinson (3 papers, 2015 to 2022). "Importantly, AGPAT1−/− mice exhibited neurological disorders, including seizures, while the AGPAT1 gene has been also identified as a gene of interest in studies for neurological diseases such as Parkinson and dementia." (PMID 35008394, 2022). "Some have been associated with neurodevelopmental disorders: schizophrenia (DIXDC1, ARVCF, MAGI2, ZIC2), ADHD (attention deficit/hyperactivity disorder) (TCERG1L), movement disorders (NOL3, TP53INP2), Huntington’s disease (H2AFY2, AGPAT1), Parkinson’s disease (LMX1B), and autism (PLXNA4, WNT2)." (PMID 25748564, 2015). "One SNP near AGPAT1 demonstrated a negative allelic effect between frontotemporal dementia, which exhibits parkinsonism and related pathology, and (immune-mediated) celiac disease; another SNP has been associated with Alzheimer’s disease." (PMID 33981329, 2021).
ovarian carcinoma (2 papers, 2022). A malignant neoplasm originating from the surface ovarian epithelium. "On the other hand, in a microarray analysis of transcriptomic profiles for the identification of ovarian cancer mRNA biomarkers in saliva, AGPAT1 was one of the seven validated genes, with expression levels significantly downregulated in ovarian cancer patients compared to healthy controls." (PMID 35008394, 2022). "AGPAT1, B2M, BASP2, IER3, and IL1B are the salivary mRNAbiomarkers for ovarian cancer detection." (PMID 37693919, 2022).
schizophrenia (2 papers, 2015 to 2022). A major psychotic disorder characterized by abnormalities in the perception or expression of reality. "AGPAT1 is involved in regulation of phospholipids, the dysregulation of which has been implicated in schizophrenia before." (PMID 36344995, 2022).
type 2 diabetes (2 papers, 2012 to 2023). "AGPAT1 (1-acylglycerol-3-phosphate O-acyltransferase 1) and type 2 diabetes: AGPAT1 is a metabolism (lipid biosynthesis) gene and plays important functions in the physiology of multiple organ systems." (PMID 36782330, 2023). "In large meta-analyses, associations between FADS1-2-3 and carotid intima media thickness, AGPAT1 and type 2 diabetes, and APOA1 and coronary artery disease were observed." (PMID 22359512, 2012).
Autoimmunity (1 paper, 2016). The occurrence of an immune reaction against the organism's own cells or tissues. "Smoking was significantly associated with hypomethylation of a DMR overlapping the promoter region of the RNF5 and the AGPAT1, which are implicated in inflammation and autoimmunity, whereas DMARD treatment induced hypermethylation of the same region." (PMID 27909437, 2016). "Thus, both RNF5 and AGPAT1 have been associated with inflammation and autoimmunity." (PMID 27909437, 2016).
breast carcinoma (1 paper, 2022). "To check if the results were based on cancer cells’ physiology; we assessed the expression of AGPAT1 and GPAT1 in other breast cancer cell lines; MDA‐MB‐231, MDA‐MB‐468 and T47D." (PMID 36149760, 2022). "Interestingly, all the three breast cancer cell lines showed a significant reduction in expression of AGPAT1 and GPAT1, generally showing that the expression pattern in the two genes is peculiar to breast cancer cells and not HeLa cells." (PMID 36149760, 2022).
cerebral infarction (1 paper, 2025). An ischemic condition of the brain, producing a persistent focal neurological deficit in the area of distribution of the cerebral arteries. "The AUC values of Pip5k1c, Nlgn2, Fzd2, Cd86, Agpat1, and Degs2 were all 1, suggesting that Pip5k1c, Nlgn2, Fzd2, Cd86, Agpat1, and Degs2 have good sensitivity and specificity for the diagnosis of cerebral infarction." (PMID 40520774, 2025). "We further analyzed the expression differences of Pip5k1c, Nlgn2, Fzd2, Cd86, Agpat1, and Degs2 between the cerebral infarction at 3, 6, and 12 h and the control group." (PMID 40520774, 2025).
colitis (1 paper, 2016). Inflammation of the colon. "Thirty-seven (37 = 58.7%) of these DMRs associated with genes, but only 6 (16.2%) of those have been implicated in either colitis (PTPRF, ELTD1, and GDNF) or CRC (PTPRF, ELTD1, PDX1, CCK, and AGPAT1)." (PMID 27006956, 2016).
COVID-19 (1 paper, 2024). A disease caused by infection with severe acute respiratory syndrome coronavirus 2. "We observed the distinct association between “severe COVID-19 or rheumatoid arthritis” with JIA that was mediated by a subset of 6p21.3 genes within cluster 8 (AGPAT1, PSMB8, TAP1, HCG4P11, HLA-DMB)." (PMID 39175752, 2024).
ischemic stroke (1 paper, 2025). A stroke disorder caused by obstruction of blood flow to the brain, due to thrombotic (local blood clot formation) or embolic (due to a blood clot or other material traveling from another site) event. "Single-gene GSEA revealed that the identified signature genes (Pip5k1c, Nlgn2, Fzd2, Cd86, Agpat1, and Degs2) converge on neuroinflammatory and apoptotic pathways critical in ischemic stroke pathogenesis." (PMID 40520774, 2025). "The results demonstrated that, in comparison to the control group, the expression of Pip5k1c, Nlgn2, Fzd2, Cd86, Agpat1, and Degs2 showed a downward trend with an increase in the onset time of ischemic stroke, and the decrease was most significant in the MCAO_12 h group (p < 0.01)." (PMID 40520774, 2025).
lipodystrophy (1 paper, 2022). A congenital or acquired disorder characterized by abnormal loss or redistribution of the adipose tissue in the body. "Interestingly, despite the homology between AGPAT1 and AGAPT2, AGPAT1−/− mice, although having reduced fat, did not develop lipodystrophy and had low plasma glucose levels." (PMID 35008394, 2022).
pelvic organ prolapse (1 paper, 2024). Abnormal descent of a pelvic organ resulting in the protrusion of the organ beyond its normal anatomical confines. "Homozygosity for Agpat1 or Cacna1a mutations led to early lethality; homozygosity for Loxl1 mutations led to pelvic organ prolapse, preventing aging." (PMID 38770563, 2024).
Stroke (1 paper, 2025). Sudden impairment of blood flow to a part of the brain due to occlusion or rupture of an artery to the brain. "Intriguingly, Agpat1 was mainly involved in ribosome and spliceosome, potentially revealing an underappreciated role of post-transcriptional regulation in stroke pathophysiology." (PMID 40520774, 2025).
type 1 diabetes (1 paper, 2016). "Increased expression of this gene has been reported in PBMCs from RA patients with active disease, and SNP genotypes of both RNF5 and AGPAT1 have been associated with susceptibility to type 1 diabetes." (PMID 27909437, 2016).
virus infection (1 paper, 2026). "AGPAT1, together with CHIKV E2, was found to localize in the early endosomes, early during the virus infection." (PMID 41700904, 2026). "AGPAT1 is a protein involved in lipid metabolism and has not been reported to have a direct role in any virus infection or as a virus receptor." (PMID 41700904, 2026).
ZIKV infection (1 paper, 2022). "DGAT1, ACAT1, AGPAT1, and AGPAT2 mRNA levels were increased after ZIKV infection (albeit < 1.5-fold compared with the levels in the mock control), indicating that ZIKV infection promotes LD biosynthesis." (PMID 36405969, 2022). "Although the expression of the DGAT1, ACAT1, AGPAT2, and AGPAT1 genes, which are involved in LD biosynthesis, was activated, fatty-acid synthases (SCD1 and FASN, but not ACC1) were significantly downregulated during ZIKV infection." (PMID 36405969, 2022).
tumor (7 papers, 2014 to 2022). "Interestingly, APOA1, FASN, FABP4, and LPL were oppositely dysregulated in liver and lung metastasis compared to the primary CRC tumour, whereas AGPAT1 was found to be significantly upregulated in lung metastasis." (PMID 35957902, 2022). "Moreover, individuals with upregulation of ABCA1 and AGPAT1 expression have an increased risk of CRC recurrence, independently of tumor stage." (PMID 29464044, 2018). "This study broaden the prognostic value of ABCA1, ACSL1, AGPAT1 and SCD genes, independently of CRC tumor stage, leading to future precision medicine approaches and “omics”-guided therapies." (PMID 29464044, 2018). "Moreover, this study highlights the utility of ABCA1 and AGPAT1 as prognosis biomarkers of recurrence in CRC, independently of tumor stage." (PMID 29464044, 2018).
cancer (3 papers, 2015 to 2022). A tumor composed of atypical neoplastic, often pleomorphic cells that invade other tissues. "While several studies have suggested the association between enhanced transcription of AGPAT2 and certain cancers or inflammation-associated diseases, neither of them have described the influence of AGPAT1 isoform on cancer prognosis." (PMID 25749516, 2015).
neurodegenerative disease (3 papers, 2019 to 2022). A disorder of the central nervous system characterized by gradual and progressive loss of neural tissue and neurologic function. "Both RNF5 and 1-acylglycerol-3-phosphate O-acyltransferase 1 (AGPAT1) have been implicated in neurodegenerative diseases." (PMID 33981329, 2021). "Meanwhile, the top hyper-methylated DMR was located near the promoter region of both AGPAT1 and RNF5, which have been reported as genes of interest in studies focusing on neurodegenerative diseases such as AD, PD and related dementias." (PMID 36418427, 2022).
infection (2 papers, 2019 to 2022). The state of being infected such as from the introduction of a foreign agent such as serum, vaccine, antigenic substance or organism. "Furthermore, in AGPAT1-depleted mosquitoes, we showed that enhanced infection was associated with increased consumption/redirection of aminophospholipids." (PMID 31815960, 2019). "Based on the association between the infection-induced phospholipidome reconfiguration and AGPAT1 down-regulation, we hypothesized that AGPAT1 mediates the phospholipidome reconfiguration that promotes DENV infection." (PMID 31815960, 2019). "One of the up-regulated genes, AGPAT1, was significantly down-regulated during infection with the New York strain at 12hpi." (PMID 36204651, 2022). "We next showed that aminoPL reconfiguration is partially mediated by infection-induced AGPAT1 down-regulation, which increases aminoPL concentrations." (PMID 31815960, 2019). "In mosquitoes, AGPAT1 depletion also partially recapitulated DENV-induced aminophospholipid increase before infection and enhanced infection by maintaining high aminophospholipid concentrations." (PMID 31815960, 2019). "Furthermore, we show that in an environment richer in aminoPLs (AGPAT1 depletion), infection reduces aminoPL concentrations at a higher and earlier rate than in a wild-type organism, while increasing virus production." (PMID 31815960, 2019). "Indeed, AGPAT1 was downregulated upon infection and its depletion partially recapitulated DENV-induced aminoPL reconfiguration both in vitro and in vivo." (PMID 31815960, 2019). "However, only AGPAT1 depletion promoted infection by maintaining high aminophospholipid concentrations." (PMID 31815960, 2019). "It is intriguing that AGPAT1 depletion only increased infection at 7 dpi." (PMID 31815960, 2019). "To test whether infection-induced phospholipidome reconfiguration is associated with AGAPT regulation, we quantified AGPAT1 and 2 expressions." (PMID 31815960, 2019). "Therefore, AGPAT1 downregulation by infection generates a pro-viral environment." (PMID 31815960, 2019). "AGPAT1 depletion partially recapitulated DENV-induced metabolic reconfiguration and enhanced infection by maintaining high phospholipid concentrations." (PMID 31815960, 2019). "Depletion of either AGPAT1 or AGPAT2 increased aminophospholipids and partially recapitulated DENV-induced reconfiguration before infection in vitro." (PMID 31815960, 2019). "Infection in AGPAT1-depleted cells, but not in AGPAT2-depleted cells, mostly increased aminoPLs as compared to infected wild-type cells." (PMID 31815960, 2019).
metabolic disease (1 paper, 2025). A congenital disorder (due to inherited enzyme abnormality) or acquired (due to failure of a metabolically important organ) disorder resulting from an abnormal metabolic process. "For example, AGPAT1 plays a role in lipid metabolism and its dysregulation could contribute to the altered adipose tissue function observed in metabolic diseases." (PMID 41373473, 2025).
AGPAT1 also shares sentences with these, for which no sentence is quoted: Alzheimer disease (1 paper); Anxiety (1); autism (1); celiac disease (1); cognitive decline (1); coronary artery disease (1); cutaneous disorder (1); dementia (1); developmental delays (1); diabetes (1); exfoliation glaucoma (1); frontotemporal dementia (1); Huntington disease (1); lichen planopilaris (1); lipid metabolism disorders (1); lung carcinoma (1); metabolic syndrome (1); movement disorder (1); multiple sclerosis (1); neurodevelopmental disorder (1); neurological disorders (1); primary angle-closure glaucoma (1); rheumatoid arthritis (1); tonic-clonic seizures (1).